IL10 (interleukin 10)
Diseases named in the same sentence as IL10 in open-access papers (continued):
Sharing a sentence is not in itself a finding about the gene and the disease.
infection (continued). "Production of the regulatory cytokine IL-10 in response to QE65 was significantly increased after gluten challenge, however a small trend for increased levels after challenge, prior to infection, was also seen." (PMID 21949691, 2011). "At 10 weeks post-infection BCG vaccinated animals exhibited very low levels of all the cytokines studied (IFNγ, TNFα, TGFβ, IL10 and IL12)." (PMID 21533158, 2011). "Collectively, these data demonstrate the capacity of a prophylactic infection with S. mansoni to attenuate the severity of collagen-induced arthritic disease, which may be due to systemic suppression of proinflammatory cytokine production and enhanced synthesis of IL-10." (PMID 21584243, 2011). "Comparisons across age groups following infection revealed that expression of MIP-1α, MCP-1, IL-10, TNF-α and IFN-γ were significantly increased by infection in preterm lambs compared to full-term lambs." (PMID 21827668, 2011). "On the other hand, PC-SA-SSG led to strong suppression of IL-10 and TGF-β production that correlated with successful resolution of infection." (PMID 21423750, 2011). "Accordingly, experimental infection with L. braziliensis leads to increased leukocyte recruitment, CCL2 and CXCL10 expression, and production of IL-10." (PMID 20559550, 2010). "In this study, we observed that although coinfected animals presented high levels of serum TNF-α during the acute phase of infection, the potential toxic effects of TNF-α were counterbalanced by the production of significant serum levels of IL-10." (PMID 20967289, 2010). "We tested cytokine production in the in vitro infections, focusing on TNF-α and IL-10 as the main representatives of the Th-1 and Th-2 responses." (PMID 20500810, 2010). "In the present study our results indicated that IL-10 expression was markedly increased and similar to the extent of up-regulated expression of IFN-γ following infection by the H or Ts strain." (PMID 21143846, 2010). "The mRNA expression of IL-10, INF-γ, and TNF in liver, kidney, and spleen throughout infection was similar in the knockout mice as compared to the wild type mice." (PMID 20403155, 2010). "However, and quite unexpectedly, neutralization of IL-17 in WT and IL-10−/− mice, resulted in a reduction in Mtb load in the spleen, which suggests that IL-17 may affect dissemination of mycobacteria to the spleen during an aerogenic infection." (PMID 20518032, 2010). "At week 6 post-infection, IFN-γ, IL-4 and IL-10 levels also showed a dramatic rise synchronously in vaccinated pigs." (PMID 20976218, 2010). "IL-10 was consistently modestly elevated in the serum of patients with CHB, but would be expected to be at higher concentrations at the site of infection in the liver and in close proximity to the cells from which it is released." (PMID 21187913, 2010). "At the acute stage of infection, besides IFN-γ, the expression of IL-4 and IL-10 in the Vac-Cha group increased significantly at week 6 post-challenge." (PMID 20976218, 2010). "We conclude that histone H3 modification-independent IL-10 induction is not sensitive to suppression by T. gondii, but that histone H3 modification-dependent IL-10 synthesis, like control of TNF-α, is blocked by infection." (PMID 19859561, 2009). "After 8 h post-challenge, both groups showed a progressive increase in IL-10 in BAL, which remained high up to d 5 post-infection." (PMID 19835595, 2009). "The L. casei group showed levels of IL-10 and IL-4 in BAL and serum significantly higher that those in the control group during the late stage of the infection." (PMID 19835595, 2009). "In IL-10−/− mice, viral replication was significantly inhibited following infection, indicating that IFN-γ is dispensable for controlling WNV infection in the model of IL-10−/− mice, particularly during the early stage of infection." (PMID 19816558, 2009).
infection (continued). "We thus next examined the levels of TNF, IL-1β, IL-2, IL-6, IL-10, and MCP-1 (also known as CCL2) in human PBMC infected by CDC1551, HN878, and HN878 pks1-15::hyg 2 and 4 days post-MTb infection." (PMID 19568431, 2009). "We analyzed the levels of IL-2, IL-4, IL-5, IL-10, IL-12(p70), GM-CSF, IFN-γ and TNF-α in the culture supernatant of macrophages 24 h post infection." (PMID 19680450, 2009). "IL-6KO mice treated with rIL-6 during the early immune response following CB3/LPS infection had significantly decreased serum levels of TNF-α, IL-10, MCP-1, MIP-1β, MIG and RANTES as well as decreases in MIP-1α." (PMID 19587788, 2009). "All genes play major roles in immune response during infection including cytokines (IL8, IL6, IL10, IL1B, and TNF) and SAA3 (an acute-phase protein), as well as PMN adhesion selectin-L (SELL) and LYZ (involved in anti-microbial defense)." (PMID 19925655, 2009). "Intraperitoneal infection with MHV68/M2.Stop increased the establishment of latency eight-fold over intranasal inoculation, yet serum IL-10 levels were very similar to those observed following intranasal inoculation." (PMID 18389062, 2008). "The infection-induced accumulation of IL-6 and IFN-γ would be predicted by their respective mRNA abundance, whereas the accumulation of IL-10 was unexpected." (PMID 18575603, 2008). "Interestingly, peripheral blood mononuclear cells stimulated with Taenia sp. GCs elicit IL-10, TGF-β and molecules associated with anti-inflammatory responses and this type of immune reaction is known to be inversely associated with the severity of infection in human NCC." (PMID 18398489, 2008). "During infection, like IL10 and TGF-β, the principal function of CD4+ CD25+ FoxP3+ Treg is the control of intense inflammation, induced at the site of infection, to avoid tissue damage." (PMID 18665224, 2008). "The production of IL-10 is consistently reduced throughout SEOV and during the persistent phase of SNV infection in rats and deer mice, respectively, revealing that IL-10 does not contribute to regulatory T cell–mediated hantaviral persistence." (PMID 19043585, 2008). "To further investigate the role of TLR2 during infection with S. pneumoniae PLN, we determined TNF-α, IL-1β, IL-10, MIP-2, KC and MPO levels in whole lung homogenates obtained 24, 48 and 72 h after inoculation." (PMID 17711480, 2008). "A variety of cytokines and chemokines were measurable during infection including: GRO, IL-1β, IL-6, IL-10, IL-12, GM-CSF, TNFα, MDC, and IL-8." (PMID 17257430, 2007). "In addition, production of TNF-α and IL-10 after stimulation with ES products differed by infection status, with hookworm-infected individuals producing significantly less, which might serve as a mechanism to minimize intestinal inflammation at the site of worm attachment in infected patients." (PMID 17576364, 2007). "Infection with B.anthracis resulted in marked upregulation of IL-6, IL-10 and IL-12 in BALF 24 hrs after infection compared to saline treated controls." (PMID 17710136, 2007). "Differently, only BCGin/DNA immunized, infected mice presented significant IL-10 production in relation to BCGsc, BCGin and DNA-HSP65 groups, on days 30 and 70 after infection." (PMID 17714584, 2007). "Other than an early spike of IL-10 detectable on day 2 post-infection, LCMVARM-infected mice had low levels of IL-10 in their serum." (PMID 17570849, 2007). "Cohorts of IL-10-/- mice were infected with 2 × 105 pfu of LCMVARM and their ability to mount T cell responses and clear virus was assayed at 8 days post infection." (PMID 17570849, 2007). "The cytokines secreted by phagocytes in response to infection include TNF-α, IL-1β, IL-6, IL-8 and IL-10." (PMID 16280065, 2005). "The cytokines secreted by phagocytes in response to infection include tumor necrosis factor (TNF)-α, IL-1β, IL-6, IL-8 as well as IL-10." (PMID 16280065, 2005).
infection (continued). "TNF-α, IL-2, IL-4, IL-10, and IL-12p70 were not produced at 4 h post-infection with any of the bacterial strains, in either HT-29 or Caco2 cell lines (data not shown)." (PMID 41459941, 2026). "In contrast, IL-10 blockade in IL-10-inducing isolates (3262, 2988) increased non-apoptotic infected cells without altering overall infection frequency, suggesting IL-10 modulates apoptotic progression in infected cells." (PMID 42067858, 2026). "However, in piglets, infection elicited substantial increases in serum inflammatory cytokines (TNF-α, IFN-γ, IL-6, and IL-10) but produced only mild clinical signs and limited pulmonary inflammation." (PMID 41971018, 2026). "Indeed, the abundance of Enterobacteriaceae or Escherichia-Shigella was positively correlated with rectal temperature at 12 and 24 h post-infection, serum TNF-α level, and jejunal IL-1β, IL-10, and TNF-α mRNA levels." (PMID 41547922, 2026). "Regardless of sex, infection induced upregulation of IL‐10, IL‐8, and TNF, alongside downregulation of CCL2 and IL‐18 in the supernatant of infected cells." (PMID 41546136, 2026). "Analysis of differentially expressed genes in the LC group compared with the CC group at day 90–180 after infection identified an increase of multiple proinflammatory markers, such as IL6, NLRP3, TNF, JAK2, CSF2, IL1B and IL10, in the LC compared with the CC group." (PMID 41388153, 2026). "In chronically S. haematobium‐infected adults with low intensities of infection, stimulation of PBMCs ex vivo with adult worm antigen (AWA) resulted in higher secretion of TGFβ and IL‐10 by female‐derived cells, but lower secretion of Th1‐associated TNF and IFNγ." (PMID 41546136, 2026). "In non‐lethal infections, early production of pro‐inflammatory cytokines such as IFN‐γ and TNF‐α supports parasite control, while timely induction of regulatory cytokines like IL‐10 and TGF‐β prevents excessive inflammation." (PMID 41461395, 2026). "However, recent studies have found that IL-10 may exhibit pro-inflammatory properties and participate in disease progression under specific pathological conditions, such as in autoimmune diseases, malignant tumors, and coronavirus disease 2019 (COVID-19) infection." (PMID 41601653, 2026). "multilocularis infection, LAG3-/-CD4+ T cells exhibited a greater propensity to differentiate into CD4+ effector T (Teff) cells and produced higher levels of IFN-γ and IL-10 in both the livers and spleens of recipient mice." (PMID 41680821, 2026). "The mRNA abundance of TNF-α, IL-1β and IL-6 were significantly up-regulated from 6 h to 24 h post infection, while those of iNOS, Arg-1 and IL-10 did not change significantly from 18 h to 24 h post infection." (PMID 40663568, 2025). "Conversely, pluronic did not impact circulating serum levels of IL-10 or hepatic Il10 transcription 2 hours post-infection in fluoxetine-treated mice." (PMID 39951524, 2025). "Blockade of IL‐10 signaling at the time of aP immunization, or B. pertussis challenge in aP‐immunized mice, attenuated the suppression of TRM responses and enhanced protection against infection in the nasal mucosa." (PMID 40629997, 2025). "Collectively, these data strongly imply that the absence of IL-10 signaling during the acute phase of the infection adversely affects the early stages of RBC differentiation (stages I to IV) in both the BM and spleen." (PMID 41471231, 2025). "Infection with P. aeruginosa can not only increase the levels of the proinflammatory cytokines IL-1β, IL-6, and TNF-α but also reduce the expression of the inhibitory cytokine IL-10." (PMID 40270824, 2025). "On the other hand, macrophages infected with L. major and treated with GXM failed to control the infection; however, neutralization of IL-10 and TGF-β significantly reduced the number of parasites." (PMID 41156732, 2025).
infection (continued). "We cannot guarantee that the high IL-10 levels we observed were present only during the chronic phase of Pc infection, nor that they persisted throughout the 50–100 days of infection, although the latter phenomenon seems likely." (PMID 40972121, 2025). "Coinfections often led to similar or slightly higher cytokine levels than single infections, except that the production of IFN-γ and IL-10 was significantly higher in the Seq(1d) RSV-IAV group than in the IAV group (P < 0.001 for both) on day 4 post-IAV challenge." (PMID 40366152, 2025). "To do so, we infected male and female mice harboring a targeted knockout of IL-10 in B cells (IL-10flox/CD19cre) with Mtb HN878 and monitored disease progression, control of bacterial replication and immunological changes over the course of infection." (PMID 40260245, 2025). "The data obtained from the experimental infection of BALB/c mice with L. (V.)guyanensis indicates a Th2-type response profile, with a predominance of IL-4 and the presence of IL-10, which apparently favored swelling progression during the chronic phase of the disease." (PMID 41017914, 2025). "We measured IL12A and IL10 mRNA levels in THP-1 cells treated with or without GM-CSF prior to infection with Legionella or stimulation with Pam3CSK4." (PMID 40470942, 2025). "Conversely, at 72 hours post-infection, the secretion of IL-6, IL-17, T-bet, TNF-α, and IFN-γ was significantly diminished (P < 0.01), while levels of TGF-β, GATA-3, IL-10, and IL-4 were significantly elevated in the Pm_OMVs-infected group compared to the Pm group (P < 0.01)." (PMID 41306977, 2025). "Treatment of C. jejuni-infected microbiota-depleted IL-10−/− mice with menthol from day two until day six post-infection did not affect the pathogen loads, but reduced the number of colonic T cells." (PMID 40395728, 2025). "Early post-infection, rises in serum IFN-γ and IL-10 were also detected." (PMID 41150385, 2025). "In addition, CMV induces production of IL-10 and TGF-β, creating an immunosuppressive milieu that limits effective T cell activity at sites of infection." (PMID 41425584, 2025). "As we studied the clinical outcome of CL in a later stage of infection (50 dpi), we did not observed significantly elevated IL-10 levels in mouse serum." (PMID 41259559, 2025). "However, we identified four chemokines and cytokines that correlate with virulence in a murine in vivo infection model: MCP-1, IL-6, IL-10 and IFN-γ." (PMID 40587585, 2025). "In our studies, wound tissue MCP-1, IL-6, and IL-10 levels were not significantly altered after 24 h of infection and LaP treatment tended to increase tissue IL-6 levels." (PMID 40068933, 2025). "Notably, IL-10+CD8+T effector cells are a reversible and transient form of effector CD8+T cells, which develop to check the exaggerated inflammation and clear the infection at its later stages." (PMID 41009359, 2025). "Recent evidence has identified IL-6, IL-8, and IL-10, alongside acute-phase reactants such as C-reactive protein (CRP) and procalcitonin (PCT), as promising biomarkers for early infection detection in neutropenic patients, supporting timely and targeted therapeutic interventions." (PMID 40647525, 2025). "TCRαβ+ and TCRγδ+ T cells are usually antagonistic and modulate inflammation and immune responses via IL-10, IL-17, IFN-γ, and other cytokines during infection with Leishmania (skin), Francisella tularensis (lung), Mycobacterium tuberculosis, simian immunodeficiency virus (SIV), and HIV." (PMID 40647626, 2025). "Consistent with the lack of effect on BR15 infection, AbII treatment did not significantly alter the levels of IL-1β, IL-6, IL-10, CCL2 (MCP-1), CCL5 (RANTES), or CXCL8 (IL-8) in BR15-infected cells." (PMID 40732762, 2025). "Infection with L. monocytogenes led to a significant increase in the mRNA levels of IL6, CXCL8, TNF, and IFNG (p < 0.01 for IL6, p < 0.001 for other cytokines), along with a significant decrease in transcription level of IL10 (p < 0.001)." (PMID 41376047, 2025).
infection (continued). "infection did not change the levels of cytokines interleukin 1β (IL-1β), IL-6, IL-10, interferon gamma (IFN-γ), and tumor necrosis factor alpha (TNF-α)." (PMID 40302747, 2025). "In our model, neutralisation of IL-13 during early CR infection did not significantly alter clinical disease parameters but resulted in reduced colonic levels of IL-10 and IL-22." (PMID 40591723, 2025). "In this respect, Hp exploits MC to evade immune clearance by favoring the production of regulatory cytokines such as IL-10 and TGF-β that dampen effective immune responses and the recruitment of regulatory T-cells (Tregs) to the site of infection, suppressing pro-inflammatory Th1 responses." (PMID 40871387, 2025). "IL-10 was not increased above background at 3 dpi, while IL-12 p40 was increased by infection and remained elevated in isotype-treated mice until 7 dpi." (PMID 40854598, 2025). "Infection with HTLV-1A/CoI-L resulted in low overall frequency of monocytes, DCs, and neutrophils producing IL-10, with elevated frequencies of those producing TNF-α in both compartments, linked to high expression of IL-6, CCL2, and IL-33 in blood and of MMP1, IL-1β, CCL3, and CCL19 in the lung." (PMID 41006234, 2025). "Conversely, after infection, the F1F3 chimera vaccine at both doses promoted mixed cytokine secreting with a strong secretion of the pro-inflammatory IFN-γ and TNF-α and the regulatory IL-10 cytokines." (PMID 40666521, 2025). "However, comparable levels of TNF, IL-6, IL-10, CXCL1, CCL3, GM-CSF, and G-CSF were observed upon CRWT and CRM12 infection." (PMID 40599135, 2025). "Multiple studies have demonstrated that biomarkers such as IL-6, PCT, IL-10, and IL-8 offer superior sensitivity and specificity compared to conventional markers like CRP, particularly in the early phase of infection and in differentiating between bacterial and viral etiologies." (PMID 40647525, 2025). "Thus, we evaluated serum cytokine levels, such as IL-1β, IL-6, IL-10, MCP-1, and IFN-γ in EV-A71 infected PLG-KO and WT mice at 2, 4, and 6 days post-infection." (PMID 40377310, 2025). "In the CsCP3-immunized group, expression levels of IFN-γ, IL-2, IL-4, and IL-10 rose rapidly post-infection but subsequently dropped to levels not significantly different from the control by the second or fourth week." (PMID 40248698, 2025). "In advanced infection stages, macrophages polarize toward an M2 phenotype, characterized by secretion of immunomodulatory cytokines such as transforming growth factor-beta (TGF-β), interleukin-10 (IL-10), and Th2-type cytokines." (PMID 41322988, 2025). "Notably, myeloid cells in AG ferrets showed significantly elevated expression of inflammatory cytokines, including IL-1β, IL-10, IL-18, NFκB1, and S100A8, as well as upregulated IFNGR2 expression throughout infection, especially 4dpi." (PMID 40794649, 2025). "The authors hypothesized that, during infection, IFN-γ drives antiviral responses, whereas IL-10, an anti-inflammatory cytokine, may inhibit the acute inflammation typical of severe that COVID-19." (PMID 40170841, 2025). "To determine whether this cytokine production influences infection outcome, we performed neutralization assays targeting TNF-α, TGF-β, and IL-10, followed by assessment of parasite burden." (PMID 41156732, 2025). "However, DC dysfunction decreases IL-12 production and increases IL-10 and TGF-β secretion, which promotes the differentiation of Treg and Th2 cells that suppress cellular immunity and contribute to the chronicity of infection." (PMID 40141021, 2025). "In mice that lacked ISG15, there were signs of more severe infection and tissue damage, along with less of the anti-inflammatory molecule IL-10." (PMID 40627782, 2025). "These cells expressed IL-10, IL-17, perforin, granzyme B, PD-1, and CD39/CD73 when restimulated with SARS-CoV-2 peptides, suggesting a unique suppressive Treg signature that persists even after the infection is resolved." (PMID 41488664, 2025).